CBX6 (chromobox 6)
Description:
Component of a Polycomb group (PcG) multiprotein PRC1-like complex, a complex class required to maintain the transcriptionally repressive state of many genes, including Hox genes, throughout development. PcG PRC1 complex acts via chromatin remodeling and modification of histones; it mediates monoubiquitination of histone H2A 'Lys-119', rendering chromatin heritably changed in its expressibility. Possibly contributes to the target selectivity of the PRC1 complex by binding specific regions of chromatin. Recruitment to chromatin might occur in an H3K27me3-independent fashion (By similarity). May have a PRC1-independent function in embryonic stem cells (By similarity).
Tractability: Small molecule: a high-quality ligand is known. PROTAC: UniProt records ubiquitination sites on it; ubiquitination databases record sites on it; its protein half-life has been measured; a small molecule that binds it is known.
Target class: Epigenetic regulator; Reader; Methyl-lysine/arginine binding protein; Chromodomain
Gene: Protein-coding gene on chromosome 22 (38,861,422 to 38,872,249, reverse strand). Ensembl gene ENSG00000183741.
Subcellular location: Nucleus; Chromosome
Subcellular location (Human Protein Atlas): Nucleoplasm; Nuclear bodies
Pathways (Reactome):
Cellular responses to stimuli: Oxidative Stress Induced Senescence
Developmental Biology: Differentiation of naive CD4+ T cells to T helper 2 cells (Th2 cells)
Gene expression (Transcription): RUNX1 interacts with co-factors whose precise effect on RUNX1 targets is not known
Signal Transduction: Regulation of PTEN gene transcription
Gene Ontology:
Molecular function: protein binding; chromatin binding; single-stranded RNA binding
Biological process: negative regulation of transcription by RNA polymerase II; heterochromatin formation; negative regulation of DNA-templated transcription
Cellular component: chromosome; nuclear body; nucleoplasm; nucleus; PcG protein complex; chromatin; PRC1 complex; heterochromatin
Genetic constraint (gnomAD): Loss-of-function variants: 7 observed, 22.53 expected, observed/expected ratio (o/e) 0.31, 90% interval 0.18 to 0.58. The upper end of that interval is the gene's LOEUF score, 0.58, which puts it in group 2 of 6, group 1 being the genes least tolerant of losing a copy. Missense variants: 511 observed, 534.44 expected, observed/expected ratio (o/e) 0.96, 90% interval 0.89 to 1.03. Synonymous variants: 297 observed, 248.8 expected, observed/expected ratio (o/e) 1.19, 90% interval 1.09 to 1.31.
Homologues: Orthologues: chimpanzee CBX6 (100% identical), macaque CBX6 (98% identical), guinea pig CBX6 (93% identical), pig CBX6 (93% identical), dog CBX6 (91% identical), mouse Cbx6 (89% identical), rat Cbx6 (89% identical), tropical clawed frog cbx6 (67% identical), Caenorhabditis elegans set-31 (16% identical), Caenorhabditis elegans hpl-1 (9% identical). Paralogues in human: CBX8 (33% identical), CBX4 (24% identical), CBX2 (23% identical), CBX7 (22% identical), NPTXR (20% identical), CBX1 (13% identical), CBX3 (13% identical), CBX5 (12% identical).
Diseases named in the same sentence as CBX6 in open-access papers:
CBX6 is named in the same sentence as 41 diseases in open-access papers, as found by Europe PMC text mining. Sharing a sentence is not in itself a finding about the gene and the disease. The quoted sentences say what the papers report.
breast carcinoma (11 papers, 2017 to 2025). "In view of these findings, the association between CBX6 levels and clinical progression of breast cancer was further explored." (PMID 30655550, 2019). "For instance, significant downregulation of CBX6 was reported in breast cancer, where its ectopic overexpression inhibited tumor progression." (PMID 40806514, 2025). "For instance, significant downregulation of CBX6 was reported in breast cancer, where ectopic overexpression inhibited tumor cancer progression." (PMID 36292141, 2022). "CBX6 mRNA was frequently downregulated in human breast cancer and ectopic expression of CBX6 reduced proliferation, migration, and invasion of breast cancer cells." (PMID 33028834, 2020). "In this study, a comprehensive analysis of The Cancer Genome Atlas (TCGA) dataset led to the identification of CBX6 as a consistently downregulated gene in breast cancer." (PMID 30655550, 2019). "In conclusion, our experiments provide evidence of significant downregulation of CBX6 expression in breast cancer." (PMID 30655550, 2019). "Based on these findings, we propose that CBX6 potentially plays a tumor suppressor role through repression of BST2 in breast cancer." (PMID 30655550, 2019). "To extend these observations, we tried to examine the expression of CBX6 by immunohistochemistry (IHC) in normal breast and breast cancer tissues." (PMID 30655550, 2019). "The discrepancy between the two datasets suggests the correlation between CBX6 expression and breast cancer patient survival needs further study." (PMID 30655550, 2019). "Overexpression of CBX6 inhibited the proliferation and metastasis capacity in breast cancer cells in vitro, altered the expression of genes involved in cell cycle regulation and other pathways." (PMID 30655550, 2019). "To determine the specific role of CBX6 in breast cancer, we comprehensively analyzed The Cancer Genome Atlas (TCGA) dataset for aberrant expression of this gene (GSE62944)." (PMID 30655550, 2019). "While a number of CBX proteins, such as CBX2, 4, 7, and 8, have been shown to play vital roles in breast cancer progression, the specific function of CBX6 in breast cancer progression remains to be elucidated." (PMID 30655550, 2019). "Exogenous overexpression of CBX6 inhibited cell proliferation and colony formation, and induced cell cycle arrest along with suppression of migration and invasion of breast cancer cells in vitro." (PMID 30655550, 2019). "Experiments from the current study demonstrated that CBX6 expression was frequently downregulated in breast cancer." (PMID 30655550, 2019). "Indeed, high expression of NFATC3, CBX6 and CNOT6L is associated with better survival in breast cancer patients." (PMID 37409119, 2023). "Our collective findings support a tumor suppressor role of CBX6 in breast cancer." (PMID 30655550, 2019). "Experiments in the current study revealed significant downregulation of CBX6 in breast cancer." (PMID 30655550, 2019). "CBX6 expression was further analyzed in breast cancer samples with different histological grades." (PMID 30655550, 2019). "The specific function of CBX6 in breast cancer is currently undefined." (PMID 30655550, 2019). "Furthermore, CBX6 has been described as a tumor suppressor in breast cancer and mesothelioma." (PMID 37409119, 2023). "Furthermore, among 150 breast cancer risk regions identified by genome-wide association studies, several ERGs identified in this study (BARX2, CBX6, KCNN4, MYEOV, PDZK1 in 300 ERGs) were included as the targets for cancer drivers, transcription factors, and signaling proteins." (PMID 35976950, 2022). "Besides, CBX6 was positively correlated with CBX7 in breast cancer." (PMID 33082469, 2020). "In addition to breast cancer, CBX6 is reported to be downregulated in glioblastomas although the underlying mechanisms are still unknown." (PMID 30655550, 2019). "The mechanisms underlying CBX6 downregulation in breast cancer are not known at present." (PMID 30655550, 2019).
breast carcinoma (continued). "CBX2, CBX4, CBX6, CBX7, and CBX8 are subunits of distinct polycomb repressive 1 complexes that have important functions in the development and progression of breast cancer." (PMID 33082469, 2020). "Examination of the TCGA dataset further confirmed the negative correlation between EZH2 and CBX6 expression patterns in breast cancer (Spearman r = −0.209, P < 0.0001)." (PMID 30655550, 2019). "Moreover, examination of TCGA dataset disclosed a marked increase in BST2 expression in breast cancer and CBX6 and BST2 were negatively correlated in breast cancer (Spearman r = −0.1804, P < 0.0001)." (PMID 30655550, 2019). "Consistently, CBX6 was significantly downregulated in breast cancer cells, compared with non-tumorigenic epithelial cells." (PMID 30655550, 2019). "Examination of the TCGA dataset revealed that CBX6 is not differentially expressed in different subtypes of breast cancer." (PMID 30655550, 2019). "Also, other CBX family members like CBX3, CBX4, CBX5, CBX6, CBX7 and CBX8 express different patterns in breast cancer compared with other cancer types cells." (PMID 29190923, 2017). "Kaplan-Meier survival analysis of the TCGA breast cancer dataset showed the overall survival time did not significantly differ between patients with high CBX6 expression and low CBX6 expression when bifurcating gene expression at the median (HR = 0.94, P = 0.61)." (PMID 30655550, 2019).
hepatocellular carcinoma (11 papers, 2017 to 2023). A malignant tumor that arises from hepatocytes. "Cbx6 is a transcription repressor, whose overexpression was shown to contribute to the progression of hepatocellular carcinoma, thus predicting a poor prognosis." (PMID 36782243, 2023). "Results revealed that high expression of CBX1, CBX2, CBX3, CBX6, and CBX8 was associated with poor survival rates of hepatocellular carcinoma patients." (PMID 35677563, 2022). "Recent studies have suggested that CBX2 and CBX6 act as oncogenes in hepatocellular carcinoma (HCC)." (PMID 34321009, 2021). "For example, high CBX6 expression promotes cell growth by regulating the S100A9/NF-κB/MAPK pathway in hepatocellular carcinoma." (PMID 34395271, 2021). "There are exceptions, however; CBX7 acts as an oncogene in lymphoma and prostate cancer, and CBX6 acts as an oncogene in hepatocellular carcinoma." (PMID 34617019, 2021). "In hepatocellular carcinoma CBX6 overexpression contributes to tumor progression and is predictive of a poor prognosis." (PMID 29383137, 2017). "Furthermore, CBX6 is known to regulate gene expression, cell replication, and differentiation, and has been demonstrated to play a significant role in hepatocellular carcinoma." (PMID 37428291, 2023). "CBX4 was elevated in Hepatocellular carcinoma whereas CBX6 was decreased in glioblastoma." (PMID 29190923, 2017). "Higher expression of CBX7 was correlated with better prognosis in hepatocellular carcinoma, whereas CBX1, CBX2, CBX3, CBX6 and CBX8 were identified as independent prognostic factors for poor overall survival." (PMID 35637952, 2022). "However, the role of CBX6 in hepatocellular carcinoma (HCC) progression and patient prognosis remains unknown." (PMID 28122351, 2017).
glioblastoma (5 papers, 2013 to 2025). The most malignant astrocytic tumor (WHO grade IV). "CBX6 mRNA was downregulated as the astrocytoma grade increased and ectopic expression of CBX6 in glioblastoma cells decreased cell proliferation." (PMID 33028834, 2020). "The results of our primary study suggest that CBX6 is downregulated in glioblastomas and its overexpression reduces cell proliferative capacity." (PMID 30655550, 2019). "Although study showed that induced CBX6 overexpression inhibited glioblastoma cell proliferation, which implying CBX6 to be a tumor suppressor in certain cancer." (PMID 29190923, 2017). "Similar results were also obtained when using T98G glioblastoma cells indicating that CBX6 has an inhibitory effect on cell growth." (PMID 24260522, 2013). "Specifically, we showed that expression of CBX6 is downregulated in glioblastoma cell lines and clinical samples and that induced CBX6 overexpression inhibited glioblastoma cell proliferation." (PMID 24260522, 2013). "We found that compared to differentiated glioblastoma cells (DGC), expression of CBX2, CBX3, and CBX5 were upregulated, while CBX1, CBX4, CBX6, CBX7, and CBX8 were downregulated." (PMID 39988672, 2025). "The expression levels of CBX6 and CBX7 are downregulated, and the expression of CBX8 is upregulated in glioblastoma samples, whereas the expression of CBX2 and CBX4 remain unchanged." (PMID 24260522, 2013).
bladder cancer (3 papers, 2023 to 2025). "We think that CBX6 reduces the tumor immune response of patients with bladder cancer by suppressing the polarization of M1 macrophages and by attracting a significant number of Tregs, resulting in a poor prognosis for these patients." (PMID 37189494, 2023). "CBX6 and CBX7 play a critical role in bladder cancer formation, as shown by the results of enrichment analysis based on their coexpressed genes, which revealed that they were associated with urothelial carcinoma and carcinoma and transitional cells." (PMID 37189494, 2023). "We investigated the methylation changes between the high- and low-expression groups of CBX6 and CBX7 and discovered that the methylation of CBX6 and CBX7 was considerably elevated in the bladder cancer group." (PMID 37189494, 2023). "For example, CBX6 and CBX7 were identified as prognostic biomarkers in bladder cancer." (PMID 37938151, 2023).
glioma (3 papers, 2013 to 2022). A benign or malignant brain and spinal cord tumor that arises from glial cells (astrocytes, oligodendrocytes, ependymal cells). "With regard to CBX6, many types of cancers harbored low expression, such as brain and CNS cancer, BC and CRC." (PMID 36140750, 2022). "However, in a cohort which includes low grade gliomas, significant survival benefits were observed for patients with low EZH2, PHF19, CBX8 and PHC2 expression, and high CBX7, CBX6, RYBP and EZH1 expression." (PMID 24260522, 2013).
liver cancer (3 papers, 2018 to 2025). An epithelial or non-epithelial malignant neoplasm that arises from the liver. "Otherwise, in liver cancer, elevated CBX6 expression was associated with a worse prognosis." (PMID 40806514, 2025). "Otherwise, in liver cancer, high expression of CBX6 was associated with a worse prognosis." (PMID 36292141, 2022). "CBX6 was also significantly related with shorter OS of liver cancers patients and was an independent prognostic factor for shorter OS of liver cancer patients." (PMID 30481161, 2018).
malignant mesothelioma (3 papers, 2020 to 2022). A malignant neoplasm of the pleura or peritoneum, arising from mesothelial cells. "In human tissues, CBX6 was localized in the nuclei of normal mesothelium and benign mesothelioma; however, in malignant mesothelioma, the nuclear staining of CBX6 was lost." (PMID 34572485, 2021). "CBX6 shows nuclear localization in normal mesothelial cells, but it is largely diminished in the malignant mesothelioma in human patients, suggesting the clinical relevance of our findings." (PMID 33028834, 2020). "In contrast, nuclear staining of CBX6 was faint in 20 cases or weak in 6 cases in 26 cases of malignant mesothelioma of various tissue origins." (PMID 33028834, 2020). "In human tissues, CBX6 localized in the nuclei of normal mesothelium and benign mesothelioma, but the nuclear staining of CBX6 was lost in malignant mesothelioma." (PMID 33028834, 2020). "Another study indicated that downregulation of CBX6 induced MMP-2 expression and an invasive phenotype in malignant mesothelioma cells." (PMID 36140750, 2022).
mesothelioma (3 papers, 2020 to 2023). A usually malignant and aggressive neoplasm of the mesothelium which is often associated with exposure to asbestos. "To test the clinical relevance of the loss of CBX6-mediated silencing in mesothelioma progression, we performed immunohistochemical staining of CBX6 in human normal mesothelium and mesothelioma tissues." (PMID 33028834, 2020). "Enhanced degradation of CBX6 in invasive mesothelioma cells and loss of nuclear CBX6 during malignant progression of mesothelioma tissues suggests that the loss of CBX6 function may contribute to the malignant progression of mesothelioma." (PMID 33028834, 2020). "Since MMP-2 is essential for collagen invasion as we shown here, MMP-2 upregulation in invasive mesothelioma cells, which might be caused by CBX6 degradation, would contribute mesothelioma invasion." (PMID 33028834, 2020). "Transcriptome analysis suggested that CBX6 regulates sets of genes involved in mesothelioma migration and metastasis." (PMID 34572485, 2021). "In this study, we showed enhanced ubiquitination and degradation of CBX6 in invasive mesothelioma compared with that in non-invasive mesothelioma." (PMID 33028834, 2020). "Using shRNA-mediated knockdown of PcG proteins, we found CBX6 as a major PcG silenced MMP-2 in non-invasive mesothelioma cells." (PMID 33028834, 2020). "Knockdown of CBX6 in mesothelioma cells altered sets of genes that potentially participate in migration and invasiveness, including MMP-2." (PMID 33028834, 2020). "In this study, we found that CBX6 in PRC1 is constantly unstable due to ubiquitination and degradation in invasive mesothelioma cells." (PMID 33028834, 2020). "Knockdown of PRC component chromobox 6 (CBX6) promoted MMP-2 expression and invasion of mesothelioma cells." (PMID 33028834, 2020). "Knockdown of CBX6 promoted MMP2 expression and invasion of mesothelioma cells." (PMID 34572485, 2021). "Thus, the knockdown of CBX6 upregulated MMP-2 expression and mesothelioma invasion." (PMID 33028834, 2020).
astrocytoma (2 papers, 2013 to 2020). "Among them, the expressions of EZH2 and PHF19 correlated positively with the astrocytoma grades, whereas the expressions of CBX7, CBX6 and EZH1 correlated negatively with astrocytoma grades." (PMID 24260522, 2013). "CBX6, CBX7 and EZH1 shared a similar pattern and correlated negatively with increasing astrocytoma grade, whereas the opposite occurred with EZH2 and PHF19." (PMID 24260522, 2013). "Interestingly, changes in EZH2, PHF19, CBX7, CBX6 and EZH1 occurred progressively as astrocytoma grade increased." (PMID 24260522, 2013).
head and neck squamous cell carcinoma (2 papers, 2023). A squamous cell carcinoma that arises from any of the following anatomic sites: lip and oral cavity, nasal cavity, paranasal sinuses, pharynx, larynx, and salivary glands. "CBX6 (chromobox protein 6) accelerates EMT in head and neck squamous cell carcinoma, resulting in cancer progression." (PMID 36639776, 2023). "High SPATS2L (HR = 1.32, p = 0.041) and CBX6 (HR = 0.43, p = 0.000033) mRNA expression was significantly correlated with short OS in head–neck squamous cell carcinoma patients." (PMID 36597889, 2023).
lymphoma (2 papers, 2021 to 2023). A malignant (clonal) proliferation of B- lymphocytes or T- lymphocytes which involves the lymph nodes, bone marrow and/or extranodal sites. "Analyses related to CBX6 include diffuse intrinsic pontine glioma, urothelial carcinoma, MIXED LINEAGE LEUKEMIA, carcinoma, transitional cell, lymphoma, follicular, gastrointestinal stromal tumors, and eosinophil count procedures." (PMID 37189494, 2023).
ovarian carcinoma (2 papers, 2020 to 2022). A malignant neoplasm originating from the surface ovarian epithelium. "Nevertheless, the prognostic value of the other five CBXs family members for predicting OS and PFS in ovarian cancer patients was either irrelevant (CBX5 and CBX8) or inconsistent (CBX4, CBX6, and CBX7)." (PMID 35155439, 2022). "However, the results showed that the prognostic significance of CBX4-8 mRNA expression for predicting OS and PFS in all patients with ovarian cancer was inconsistent (CBX4, CBX6 and CBX7) or irrelevant (CBX5 and CBX8)." (PMID 32742466, 2020).
prostate carcinoma (2 papers, 2021 to 2025). A carcinoma that arises from epithelial cells of the prostate gland. "Then we further clarified the expression of CBX family members in prostate cancer, which result showed that CBX5, CBX6 and CBX7 were significantly down-regulated in prostate cancer tissues, while CBX3, CBX2, CBX4 and CBX8 was notably up-regulated." (PMID 40861818, 2025).